RNU6-3P (RNA, U6 small nuclear 3, pseudogene)
Synonyms: U6-3; RNU6-3
Gene: Small nuclear RNA gene on chromosome X (141,118,030 to 141,118,136, reverse strand). Ensembl gene ENSG00000207041.
Homologues: Orthologues: dog U6 (100% identical), mouse Gm22295 (100% identical), rabbit U6 (100% identical), rat U6 (100% identical). Paralogues in human: RNU6-1 (100% identical), RNU6-2 (100% identical), RNU6-4P (100% identical), RNU6-5P (100% identical), RNU6-6P (100% identical), RNU6-9 (100% identical), RNU6-12P (99% identical), RNU6-13P (99% identical), RNU6-17P (99% identical), RNU6-18P (99% identical), RNU6-25P (99% identical), RNU6-32P (99% identical), and 1288 more.